STAT3 (signal transducer and activator of transcription 3)
Diseases named in the same sentence as STAT3 in open-access papers (continued):
Sharing a sentence is not in itself a finding about the gene and the disease.
gastric cancer (continued). "Studies have shown that IL-6 upregulates fascin expression levels in MKN45 gastric cancer cells, thereby promoting signal transduction and activator of transcription 3- (STAT3-) dependent migration and invasion." (PMID 34194957, 2021). "The therapeutic potential of targeting STAT3 in the treatment of gastric cancer deserves further investigation." (PMID 33718136, 2021). "Activation of STAT3 by IL-17A impacts quiescent gastric cancer stem cells (CSCs), which showed EMT-like transformation after exposure to IL-17A." (PMID 34944729, 2021). "This study elucidated that β-blocker pretreatment improved the antitumor efficacy of an oncolytic virus, T1012G, by regulating STAT3-PKR dependent antiviral response in gastric cancer cells in response to viral infection and type I IFNs." (PMID 34544479, 2021). "We also performed tissue microarray to determine the correlation between STAT3 and YWHAZ expression in gastric cancer tissue samples (n = 60), showing a positive trend of STAT3 and YWHAZ (r = 0.208)." (PMID 33718136, 2021). "Inhibition of STAT3 pathway significantly potentiated cisplatin‐induced cell death in gastric cancer cells." (PMID 34375503, 2021). "For example, the STAT3/c-Myc axis regulates the energy metabolism of gastric cancer cells by synergistically communicating with the mTOR/PKM2 pathway." (PMID 34608390, 2021). "Aberrantly elevated STAT3 activity has been found in the majority of cancer, including gastric cancer." (PMID 34375503, 2021). "IL-11, a member of the IL-6 family, promotes the progression of chronic inflammation to gastric carcinoma via gp130-mediated activation of STAT3 and STAT1 signaling in human gastric carcinogenesis." (PMID 34210998, 2021). "The keywords included “STAT3 & gastric cancer”, “drug & STAT3 & gastric cancer”, “lncRNA & STAT3 & gastric cancer” and “miR & gastric cancer & STAT3”." (PMID 32545648, 2020). "miR-216a plays a role in the inhibition of gastric cancer metastasis via targeting JAK2/STAT3-mediated EMT, thereby suggesting its role in tumor suppression and, ultimately, gastric cancer development." (PMID 32992741, 2020). "Among these, we also found the drug cerulenin targeting FASN in stomach cancer was correlated with STAT3 positively (r = 0.555)." (PMID 32486001, 2020). "Curcumin inhibits Bcl-2, Bcl-XL, VEGF, c-Myc, ICAM-1, EGFR, STAT3 phosphorylation, and cyclin D1 genes involved in the various stages of breast, prostate, and gastric cancer proliferation, angiogenesis, invasion, and metastasis." (PMID 33178666, 2020). "It was shown that overexpression of RNF180 in gastric cancer cells can reduce STAT3 activation, attributed to increased RhoC proteasomal degradation." (PMID 32915198, 2020). "STAT3 overexpression in gastric cancer cell lines leads to increased PVT1 levels, while STAT3 knockdown results in PVT1 transcriptional downregulation." (PMID 32083000, 2020). "It has been recently reported that STAT3 can bind to the promoter region of the EZH2 gene in gastric cancer cells, implicating STAT3 as a direct regulator of EZH2." (PMID 33086505, 2020). "Further analysis of the cancer genome atlas (TCGA) database identified a significant upregulation of STAT3 in gastric cancer tissues, and a positive correlation between the expression of STAT3 and MSK1." (PMID 32041943, 2020). "In our study, we found that CD40, STAT3 and PD-L1 are the targets of miR-502-5p in gastric cancer cells by bioinformatics analysis and luciferase reporter assay." (PMID 32821248, 2020). "PLB was a potential regulator of cellular growth, migration, invasion, and apoptosis via the upregulation of SHP1 expression and inhibition of jaK2/Stat3 pathway in gastric cancer cells." (PMID 33344645, 2020). "It is documented that Notch, STAT3 and Twist signallinginteractions in gastric carcinoma have a significant role in promoting the growth of gastric cancer." (PMID 34803268, 2020).
gastric cancer (continued). "Over-activation of STAT3 is conducive to tumor invasiveness by up-regulation of FAK in gastric cancer cells." (PMID 32045997, 2020). "Bazedoxifene has also been shown to block STAT3 activation by IL-11 in human cancer cell lines, and reduce the tumor burden in murine models of gastric cancer." (PMID 32765502, 2020). "In gastric cancer, estrogens stimulate CAFs secretion of IL-6, thereby promoting signal transducer and activator of transcription (STAT)-3 pathway-dependent cancer cells proliferation and invasion." (PMID 33553157, 2020). "Using mouse models of gastric cancer, it has been reported that upregulation of IL-6 and activation of STAT-3 in H. pylori-infected gastric cancer ensues to activation of JAK/STAT signaling cascade." (PMID 33569347, 2020). "In this study, we worked out that H. pylori infection leads to higher mRNA expression of IL-6, JAK-2 and STAT-3 at the local site of infection which better explains the progression of gastric cancer at the molecular level." (PMID 33569347, 2020). "A similar correlation was noted in the case of transcription factor STAT-3 expression in the group of patients with breast, lung or stomach cancer with neoplastic cachexia compared to patients with these types of neoplasms without cachexia and healthy people." (PMID 33327591, 2020). "Another methyltransferase (EZH2) is regulated by STAT3 and participates in anti-apoptosis in gastric cancer cells." (PMID 33023006, 2020). "The expressions of CD40 and STAT3 were decreased with the transient transfection of miR-502-5p in two gastric cancer cell lines by qRT-PCR and western blot." (PMID 32821248, 2020). "Gastric cancer growth was hindered by the inhibition of STAT3-triggered VEGF, and tumor invasion was also suppressed by caspase activation and pro-inflammatory cytokine-triggered MMP regulation by eupatilin treatment." (PMID 32503295, 2020). "Gastric cancer tumors were also found to have increased levels of phosphorylated STAT3 compared to healthy tissue." (PMID 33521321, 2020). "A similar result was reported for HER2-overexpressing breast and gastric cancers, where hyperactivated STAT3 signaling-mediated trastuzumab resistance occurred via a feedback loop comprising FN/EGF/IL-6 upstream mediators." (PMID 32872659, 2020). "As in HNC, gastric cancer cell lines exhibit IL-6-mediated STAT3 activation, which leads to increased cell survival and epithelial to mesenchymal transition in vitro." (PMID 33521321, 2020). "LINC00152, which we later termed STAiR18 due to its STAT3-dependent expression, was identified in 2013 via expression profiling in gastric cancer." (PMID 32041604, 2020). "CAFs also secrete IL-11 promoting chemoresistance in gastric cancer through JAK/STAT3/Bcl-2 signaling pathway activation." (PMID 32499779, 2020). "It plays an extremely important role in promoting the occurrence and development of gastric cancer, and chronic STAT3 activation is a key event to induce the occurrence and development of gastric cancer." (PMID 32831016, 2020). "It has been shown that knockdown of endogenous DARPP-32 increases TRAIL-induced apoptosis in gastric cancer cell lines through activation of SRC/STAT3 signalling, which contributed to our rationale for selecting TRAIL as an inducer of apoptosis." (PMID 32499571, 2020). "Trastuzumab treatment rendered resistance to itself, facilitated epithelial-to-mesenchymal transition and enhanced metastatic potential in gastric cancer cells through an IL6/STAT3/Jagged-1/Notch positive feedback loop." (PMID 32872659, 2020). "This is in agreement with several recent studies on gastric cancer, which show that pantoprazole interfered with STAT3 signaling in different modes." (PMID 32164284, 2020). "CYT997 induces autophagy and apoptosis in gastric cancer by triggering mitochondrial ROS accumulation to silence JAK2/STAT3 pathway." (PMID 32576206, 2020).
gastric cancer (continued). "For instance, lncRNA plasmacytoma variant translocation 1 (PVT1) activates STAT3, which leads to an upregulation of VEGF in gastric cancer." (PMID 32992718, 2020). "In contrast, it has been reported that FAS signaling promotes gastric cancer progression by activating STAT3 signaling." (PMID 32963220, 2020). "Among the miRNA studied in cell lines, miR148a targets CCK-BR via the inactivation of STAT3 and Akt and is identified as a tumor suppressor in human gastric cancer." (PMID 32992741, 2020). "A synergistic inhibition of survivin and STAT3 level resulting in enhanced cell death were observed in AGS gastric cancer cells after treatment with BBR with 5-FU." (PMID 33167519, 2020). "For instance, LMP2A was found to induce the phosphorylation of STAT3 that activates DNMT1 transcription and leads to the loss of PTEN expression, a common phenomenon observed in EBV-associated gastric carcinoma." (PMID 32748879, 2020). "In this study, we examine additional STAT3 targets that are epigenetically silenced by DNA methylation in gastric cancer, representing sensitive biomarkers for noninvasive detection of gastric cancer." (PMID 31194837, 2019). "According to many recent studies, activated JAK2/STAT3 signaling has been observed in several kinds of tumors such as lung, prostate, and gastric cancers." (PMID 31540495, 2019). "The closest example reported so far is a synergism between inhibition of pan class I PI3K and STAT3 in KRAS mutant-driven gastric cancer cells." (PMID 30755611, 2019). "In this regard, we performed Illumina 850K methylation microarray analysis in bisulphite-treated genomic DNA from AGS gastric cancer cells, and cells depleted of STAT3." (PMID 31194837, 2019). "On the other hand, gastric cancer tissues showed high expression levels of nuclear STAT3, as compared to normal gastric tissues (P < 0.001)." (PMID 31292446, 2019). "Our previous studies showed that aberrant activation of JAK/STAT3 signaling confer epigenetically silences STAT3 target genes in gastric cancer." (PMID 31194837, 2019). "In this study, we reported for the first time that the polarization and generation of pro-tumor M2-like macrophages was strikingly triggered by GC-MSCs in gastric cancer through activation of the JAK2/STAT3 signaling pathway via high secretion of IL-6/IL-8." (PMID 31801938, 2019). "In this study, we found that the putative STAT3 target, SPG20, is epigenetically silenced in gastric cancer, similar to our previous findings of two other STAT3-epigenetically silenced targets, NR4A3 and GATA3." (PMID 31194837, 2019). "Eupatilin has a significant therapeutic effect on gastric cancer, and it inhibits the growth of gastric cancer cells by blocking STAT3-mediated vascular endothelial growth factor expression." (PMID 31179326, 2019). "Our data indicated that HOXA11 regulated adhesion, migration and invasion and anti-apoptosis of gastric cancer cells through modulating Stat3 activation can be abolished by BBI608." (PMID 31695791, 2019). "A previous study showed that inhibition of STAT3, which is constitutively activated in gastric cancer cells, represses survivin expression." (PMID 30914735, 2019). "Taken together, SPG20, a potential STAT3 target, is frequently methylated in gastric cancer, representing a novel noninvasive biomarker for early detection of this deadly disease." (PMID 31194837, 2019). "According to recently reports, Stat3 /c-Myc signaling pathways induced tumor development in gastric cancer." (PMID 31085800, 2019). "To further explore the mechanism of ALA-mediated downregulation of MUC4, we cotransfected human gastric cancer cells with STAT3 siRNA and STAT3 overexpression construct." (PMID 31915505, 2019). "To further investigate the clinical significance of this phenomenon, we performed Illumina 850K methylation microarray analysis in AGS gastric cancer cells, and cells depleted of STAT3." (PMID 31194837, 2019).
gastric cancer (continued). "A recent study reported that TRX potentiates 5-fluorouracil treatment in human gastric cancer by suppressing the STAT3/NF-κB and Bcl-2 signaling pathways." (PMID 31182097, 2019). "Using AGS and STKM2 gastric cancer cell lines, we confirmed by Western blot analysis the activation and increase of phospho-STAT3 (Y705) in control cells after IL6 stimulation (100 ng mL−1) for 30 min." (PMID 31292446, 2019). "ALA inhibits both proliferation and invasion of gastric cancer cells by suppression of STAT3-mediated MUC4 gene expression." (PMID 31915505, 2019). "Collectively, the data demonstrated that HOXA11 and Stat3 form a positive-feedback loop which enhances the stemness of gastric cancer cells, subsequently resulting in promotion of migration and invasion, adhesion and resistance to apoptosis." (PMID 31695791, 2019). "Using IHC on gastric cancer tissue microarrays, we evaluated the protein expression of TFF1 and STAT3 in human gastric cancer and normal tissue samples." (PMID 31292446, 2019). "IL-22 facilitated the invasion of gastric cancer cells by cancer-associated fibroblasts through ERK and STAT3 signaling." (PMID 31528235, 2019). "Taken together, these results implicate Genipin in the induction of apoptotic cell death via JAK2/Stat3-regulated Mcl-1 suppression, suggesting that Genipin can potentially be an effective therapy for treating gastric cancer." (PMID 31351462, 2019). "High expression levels of signal transducer and activator of transcription-3 (STAT3), p-STAT3, and HIF-1α in gastric cancer tissues for positive VM were associated with metastasis, degree of differentiation, and prognosis." (PMID 31993365, 2019). "Collectively, these experiments indicated that HOXA11 is the target gene of transcription factor Stat3, and both of them form a positive-feedback loop regulating the malignant phenotype of gastric cancer cells." (PMID 31695791, 2019). "The combination of 5-FU and BBR showed synergistic inhibition of survivin and STAT3 levels, thereby enhancing the death of gastric cancer cells." (PMID 31208348, 2019). "Here, we investigated the relationship between the anticancer effect of Genipin and signal transducer and activator of transcription (Stat3)/myeloid cell leukemia-1 (Mcl-1) in human gastric cancers." (PMID 31351462, 2019). "It suppressed the JAK2/STAT3 pathway of gastric cancer cells in vitro and inhibited tumor growth in a xenograft model of gastric cancer in vivo." (PMID 31100782, 2019). "Although several polymorphisms have been linked to gastric cancer, we focused on polymorphism in the SLC39A6 (LIV-1) gene because it is a downstream target of the STAT3 oncoprotein and promotes cancer progression by increasing cell growth and differentiation." (PMID 31703635, 2019). "STAT3, a pleiotropic transcription factor activated downstream of cytokines, is overexpressed in gastric cancer stem cells and metastatic tumor samples." (PMID 31024835, 2019). "It suppresses gastric carcinoma proliferation by inducing apoptosis in tumor cells, activating immune cells to release cytokines, and suppressing the STAT3, VEGF, HIF-1α, and DEC1 signaling transduction pathways." (PMID 30871059, 2019). "To assess the role of STAT3 in gastric carcinogenesis, we induced gastric cancer in Stat3Δgec mice using the chemical carcinogen N-methyl-N-nitrosourea (MNU)." (PMID 29849601, 2018). "Reinforced SHP-1 expression in gastric cancer cells effectively inhibits STAT3 activity and its target genes such as cyclin D1, matrix metalloproteinases-9 (MMP-9), vascular endothelial growth factor-1 (VEGF-1), and survivin." (PMID 29409467, 2018). "Phosphorylation of STAT3 and Twist promoted gastric cancer progression were regulated by Notch 1 receptor intracellular domain." (PMID 29849934, 2018). "ATO effectively inhibits cellular invasion, EMT, and tumorigenesis in gastric cancer cells which are mediated by dephosphorylation of JAK2/STAT3 through increase of SHP-1 expression." (PMID 29409467, 2018).
gastric cancer (continued). "Another report also indicated that the antitumor effect of luteolin, a plant flavonoid, involved the suppression of the phosphorylation (Tyr705) of STAT3 through binding of Hsp90 to STAT3 to promote its interaction to SHP-1 in gastric cancer cells." (PMID 29890785, 2018). "Contrastingly, lung, ovarian, and gastric cancers showed the relationship between overexpression of STAT3 and overall low survival rates." (PMID 29423040, 2018). "Inflammation can initiate carcinogenesis in various organs, and continuous activation of STAT3 plays an important role in the initiation of inflammation and cellular transformation in gastric cancer and in several other cancers." (PMID 29849601, 2018). "Inhibition of STAT3 has also been used as a novel treatment option for gastric cancer and cancers in other organs." (PMID 29849601, 2018). "Several other drugs or compounds can also effectively dephosphorylate JAK2/STAT3 by inducing SHP-1 expression in gastric cancer, including multiple kinase and other natural compounds." (PMID 30202514, 2018). "Although activation of STAT3 induced by Helicobacter has been reported in gastric cancer cell lines and H. felis-infected mice, the precise role of STAT3 in Helicobacter-induced gastric inflammation and metaplasia is unclear." (PMID 29849601, 2018). "Reduction of GBM43 migration following STAT3 inhibition validated previous studies where STAT3 silencing impaired the migration of gastric carcinoma and GBM cells, likely due to decreased activity of RhoA and matrix metalloproteinases (MMPs) expression." (PMID 29566069, 2018). "CXCL1 expression in gastric cancer was shown to be associated with vascular endothelial growth factor (VEGF) and p-STAT3 expression, advanced tumor stage and poor prognosis." (PMID 28575019, 2017). "Recently, SIRT1 was shown to inhibit the proliferation of gastric cancer cell lines in vitro by repressing STAT3 activity." (PMID 28061480, 2017). "Subsequently, we hoisted STAT3 expression in gastric cancer cells by transfecting STAT3 plasmid and activated it by stimulating with IL-6." (PMID 29152078, 2017). "Our study was the first to investigate the collaborating effects of SIRT1 and STAT3 in gastric cancer patients." (PMID 28061480, 2017). "Of these, one study showed contrasting data that SIRT1 inhibited STAT3 activity in gastric cancer cell lines in vitro." (PMID 28061480, 2017). "To determine the correlation between SIRT1 expression and STAT3 activity during gastric cancer development, we performed the Spearman's correlation analysis in all tissues including the NG mucosa, PL, EGC and AGC tissues." (PMID 28061480, 2017). "More recently, the JAK/STAT signaling cascade was also found to regulate gastric cancer growth and survival via cell apoptosis and cell cycle shift induction, such that STAT3 inhibition increases apoptosis and arrests cells in the G1 phase." (PMID 29383166, 2017). "Several gastric cancer cell lines showed the presence of constitutively-active STAT3, which functions to facilitate cell survival via upregulating the expression of its downstream target genes such as Survivin and Cyclin D1." (PMID 29383166, 2017). "STAT3 and survivin signaling has been shown to be involved in chemotherapeutic drug resistance of gastric cancer." (PMID 28611316, 2017). "IL‐6 also induces EMT in ovarian cancer cells, similarly via the JAK2/STAT3 signaling pathway, in head and neck squamous cell carcinoma cells, in gastric cancer cells, and in uterine cervix cancer cells (in a STAT3‐Slug‐dependent way)." (PMID 28599100, 2017). "Researchers also showed that CAFs induced EMT in gastric cancer cells via secreting IL-6 that activated JAK2/STAT3 signaling pathway." (PMID 29383119, 2017). "STAT3 is also involved in several other hallmarks of gastric cancer that include cell migration and invasion." (PMID 29383166, 2017).